ARID1A (AT-rich interaction domain 1A)
Diseases named in the same sentence as ARID1A in open-access papers (continued):
Sharing a sentence is not in itself a finding about the gene and the disease.
cancer (continued). "We found that conditional deletion of Arid1a alone in endometrial epithelial cells was insufficient to induce neoplastic transformation, whereas conditional deletion of Pten led to endometrial hyperplasia that progressed to carcinoma without myometrial invasion." (PMID 32483112, 2020). "Finally, we also reviewed PIK3CA, CTNNB1, and ARID1A, as well as KRAS and BRAF, for somatic mutations in these genes have been reported to occur in EOC subtypes and corresponding cell lines most often representing other non-HGS subtype cancers." (PMID 26622941, 2015). "Subsequent to initial expansion, mutations in these loci as well as ARID1A and SMARCA4 may show a local selective advantage but do not expand far: The spatial structure of the Barrett's segment remains stable during surveillance even in patients who go on to cancer." (PMID 33664784, 2021). "Of the top 20 genes in TCGA or MSKCC, AMER1, SOX9, ARID1A and TCF7L2 were not included in our cancer panel." (PMID 34074070, 2021). "Similarly, in a study of head and neck cancer, cancer cells expressed high levels of NANOG, OCT4, SOX2 and EpCAM when ARID1A was absent." (PMID 40429787, 2025). "Interestingly, unlike ARID1A, and in contrast to its effect in our screen, SMARCB1 is a prototypical pan-cancer essential gene." (PMID 37554444, 2023). "AT-rich interaction domain 1A (ARID1A), a critical portion of the SWItch/sucrose non-fermentation (SWI/SNF) chromatin remodeling complexes, shows one of the most frequent mutant genes across different human cancer types." (PMID 35421925, 2022). "However, a comprehensive analysis of ARID1A alteration frequency and its predictive value for ICI treatment outcome in diverse cancers has not yet been investigated." (PMID 31949479, 2020). "However, a comprehensive analysis of ARID1A alteration frequency and its predictive value for ICI treatment outcome in cancers has not yet been investigated." (PMID 31949479, 2020). "Wild-type ARID1A and ARID1B are located at the promoter of CD274 in OCCC cells (shown in the human OVCA429 and RMG1 cell lines, as well as mouse ovarian ID8-Defb29/Vegf cancer cells), although ARID1B was not able to influence the levels of CD274 in ARID1A knockout (KO) cells." (PMID 39272926, 2024).
adenocarcinoma (24 papers, 2019 to 2025). A common cancer characterized by the presence of malignant glandular cells. "Molecularly, G12V, and G12D are the most common KRAS mutations in mesonephric-like adenocarcinoma, and concurrent ARID1A and PIK3CA mutations are relatively common, with 1q copy number gain being the most common." (PMID 38444000, 2024). "We identified frequent CNVs of the ATRX and RB1 genes in NENs and key driver mutations of the ARID1A, PIK3CA, CTNNB1, and MYC genes in nNENs, especially adenocarcinomas." (PMID 34422662, 2021). "In conclusion, this study describes for the first time the importance of a failure of the SWI/SNF ATPase subunit ARID1A in a large number of adenocarcinomas of the oesophagus." (PMID 31906887, 2020). "KRAS, ARID1A, ABL1, ATM, RET, and CDH1 mutations have been detected in the mesonephric adenocarcinomas containing sex cord-like pattern; among these genes, KRAS mutation was the most frequent." (PMID 31739799, 2019). "Finally, we observed a trend toward significant decreases in ARID1A and CDKN2A mutations across CCNE1-amplified EG adenocarcinoma." (PMID 38717153, 2024). "H&E image of case 17 (A, × 40) showed the coexistence of normal glands, well-differentiated adenocarcinoma components, and undifferentiated components in which SMARCA2 expression was reduced (B, × 200), and ARID1A expression was intact (C, × 200)." (PMID 36464671, 2022). "This study aimed to investigate the clinical relevance of immunohistochemical expression of proteins of the SWI/SNF complex, SMARCA2, SMARCA4 SMARCB1, ARID1A, ARID1B, and PBRM1 in 477 adenocarcinomas of the stomach and gastroesophageal junction." (PMID 34359794, 2021).
infection (15 papers, 2018 to 2025). The state of being infected such as from the introduction of a foreign agent such as serum, vaccine, antigenic substance or organism. "The authors found that AT-rich interactive domain-containing protein 1A (ARID1A) was a pro-viral gene in the case of infection by SARS-CoV-2 and MERS-CoV viruses." (PMID 35444632, 2022). "In both ARID1A-knockdown and ARID1A-knockout cells, the infection efficiency was markedly increased by 3- to 6-fold and 15-fold, respectively." (PMID 34469459, 2021). "We demonstrated that EVs produced by cancer cells upon infection with VSVΔ51 encoding an amiRNA targeting ARID1A, but not a non-targeting amiRNA, can sensitize uninfected cells to GSK126." (PMID 36674550, 2023). "One such amiRNA that we found targets transcripts encoded by the cellular gene ARID1A, which enhanced infection in tumors but not normal cells." (PMID 36674550, 2023). "Similarly, ARID1A protein expression remained constant in splenocytes of mice after in vivo infection with VSV." (PMID 34315861, 2021). "The dynamic acetylations identified here may contribute to the regulation of ARID1A activity to impact viral or host gene expression during infection." (PMID 30470744, 2018). "In this study, we identify ARID1A, PLEC and HDAC4 as predicted amiR-4 targets and show reduced gene expression and protein levels following VSVΔ51-amiR-4 infection." (PMID 35393414, 2022). "As siARID1A having a milder effect on infection than siBRG1 was already observed, the inhibitor results further highlight the importance of the BRG1/BRM ATPase activity for KSHV infection over the core subunit ARID1A." (PMID 40894008, 2025). "We found that the gene products encoded by ARID1A, PLEC and HDAC4 but not MCM2 were specifically decreased following infection with VSV∆51-amiR-4 as shown by RT-qPCR and immunoblotting analysis." (PMID 35393414, 2022). "Cells lacking the ARID1A gene are significantly more sensitive than their parental counterparts to VSV∆51 infection (P value < 0.0001 at all MOIs)." (PMID 35393414, 2022). "For example, ARID1A, a component of the DNA-binding barrier-to-autointegration factor SWI/SNF complex, displays a threefold decline in acetylation on K25, K71, and K1905 at 48 hpi, and this decline persists later in infection." (PMID 30470744, 2018).
neurodevelopmental disorder (8 papers, 2019 to 2023). A behavioral and cognitive disorder with onset during the developmental period that involves impaired or aberrant development of intellectual, motor, or social functions. "ARID1A and TRIO were already associated with neurodevelopmental disorder, and the missense mutations in these genes were selected as potential causal variants in proband 18 and 19, respectively." (PMID 29463886, 2019). "A significant number of these genes (CHD3, SETD1A, KAT6A, SETBP1, TNRC6B, ZFHX4, ARID1A and TRIO) have been associated with neurodevelopmental disorders with or without speech problems." (PMID 29463886, 2019).
gynecological tumors (6 papers, 2018 to 2025). "As part of the goal of creating a biomarker-based diagnostic test for OC, this pilot study examined nine main gene expression biomarkers of the Notch and Wnt pathways and the OC susceptibility gene ARID1A for expression changes in patients with gynecologic tumors." (PMID 40002854, 2025). "In addition, gynecologic tumor tissue was analyzed for promoter methylation of ARID1A and three homeobox (HOX) related genes." (PMID 40002854, 2025). "Although the ARID1A gene is the second most mutated gene in non-HGSOC OC, its loss in gynecologic tumor precursors such as endometriosis could be caused by promoter hypermethylation as well." (PMID 40002854, 2025). "ARID1A deficient clear cell carcinoma of the ovary or endometrium is sensitive to ATR inhibition, while the combination of ATR and PARP inhibition has activity in other gynecological tumors, irrespective of ARID1A status." (PMID 34518240, 2021).
hematological malignancies (5 papers, 2018 to 2023). "It has previously been shown that ARID1A is intolerant to variation (LoF and missense mutations), consistent with its prominent somatic role in multiple tumors, including hematological malignancies." (PMID 29389935, 2018). "Indeed, as discussed in previous sections, many SWI/SNF subunits (including the widely mutated ARID1A and SMARCA4) play specific roles in the differentiation of lymphoid and myeloid lineages and in the maintenance of some hematological malignancies." (PMID 36810086, 2023). "Further studies are warranted to investigate whether the impaired differentiation in many hematological disorders including B-cell malignancies and APL is probably in part caused by loss-of-function mutations of ARID1A." (PMID 30858552, 2019). "Overall, our findings demonstrate that simultaneous Arid1a loss and β-catenin activation in single hepatocytes, occurring in a physiological but non-cancerous context, are responsible for a major hematological disorder that is linked to de novo expression and subsequent secretion of hepatic Epo." (PMID 33084574, 2020). "For example, mice lacking ARID1A can be crossed with murine models of hematological malignancies for preclinical studies to test precision therapies." (PMID 30858552, 2019). "In addition, even in those hematological malignancies in which SWI/SNF alterations are not a major hallmark, inactivating mutations in SWI/SNF genes, especially ARID1A, are usually present at low frequencies (≤ 5%)." (PMID 36810086, 2023).
gastrointestinal tumors (4 papers, 2018 to 2024). "AT-rich interaction domain 1 (ARID1A) is a pivotal gene with a significant role in gastrointestinal tumors which encodes a protein referred to as BAF250a or SMARCF1, an integral component of the SWI/SNF (SWItch/sucrose non-fermentable) chromatin remodeling complex." (PMID 38893181, 2024). "ARID1A has been intimately linked to intestinal differentiation programs and colon carcinogenesis." (PMID 36006697, 2022). "It was shown that gastrointestinal tumors with ARID1A mutations demonstrated high immune activity." (PMID 34572812, 2021). "Although subtle differences in cell morphology and the pattern of E-cadherin staining were noted in cells with reduced Arid1a levels, no pancreas degeneration or exocrine insufficiency was observed despite sustained Arid1a knockdown." (PMID 30014851, 2018).
hematological cancers (3 papers, 2022 to 2023). "Regarding ARID1A, about half of its mutations found across different hematological and non-hematological cancers are truncating (mainly nonsense or frameshift)." (PMID 36810086, 2023). "Various SWI/SNF genes, such as ARID1A/1B/2 and SMARCA2/4, are recurrently mutated across a wide variety of hematological and non-hematological cancers, whereas others, such as BCL7A, are specifically mutated in certain hematological malignancies." (PMID 36810086, 2023). "To confirm this differential growth effect of proteasome inhibition on ARID1A wild-type and mutant lines, we applied physiological concentrations of oprozomib, a second-generation proteasome inhibitor in trial for the treatment of hematological cancers, and measured the difference in growth rate." (PMID 37028423, 2023).
genetic disorder (2 papers, 2020 to 2022). "This genetic disorder is caused by de novo mutations of ARID1A (CSS2; 1p36.11; MIM 614607), ARID1B (CSS1; 6q25.3; MIM 135900), DPF2 (CSS7; 11q13.1; MIM 618027), SMARCA4 (CSS4; 19p13.2; MIM 614609), SMARCB1 (CSS3; 22q11.23; MIM 614608) or SMARCE1 (CSS5; 17q21.2; MIM 616938) genes." (PMID 32916978, 2020). "Mutations in ARID1A cause Coffin‐Siris syndrome (CSS), a rare genetic disorder with severe neurodevelopmental deficits." (PMID 36385502, 2022).
congenital malformation syndrome (1 paper, 2022). "ARID1A mutations can cause CSS, a rare congenital malformation syndrome with severe neurodevelopmental deficits, which indicates that ARID1A could be related to cognition." (PMID 36385502, 2022).
ARID1A also shares sentences with these, for which no sentence is quoted: small cell carcinoma of the ovary (5 papers); bile duct cancer (3); follicular lymphoma (3); intraductal papillary mucinous neoplasms (3); Nicolaides-Baraitser syndrome (3); transitional cell carcinoma (3); uterine serous carcinomas (3); viral hepatitis (3); acute myeloid leukemia (2); adenoid cystic carcinoma (2); anaplastic thyroid cancer (2); B-Cell lymphoma (2); chronic gastritis (2); chronic hepatitis B (2); Coffin-Siris syndrome 2 (2); colorectal adenoma (2); developmental delay (2); Epstein-Barr virus infection (2); Kabuki syndrome (2); latent infection (2); liver fibrosis (2); mucinous neoplasm (2); pancreas (2); papillary serous carcinoma (2); uterine fibroids (2); acinar cell carcinoma (1); acute leukemia (1); adenocarcinomas of the bladder (1); adenosarcoma (1); adenosquamous carcinoma (1).
A further 111 diseases each share a sentence with ARID1A in 1 paper.